IL1B (interleukin 1 beta)
Diseases named in the same sentence as IL1B in open-access papers (continued):
Sharing a sentence is not in itself a finding about the gene and the disease.
lupus (continued). "According to previous research, miR-339-5p inhibited the expressions of the proinflammatory factors IL-6, IL-1β, and TNF-α by abolishing NF-κB activity and miR-361-5p is downregulated in interferon-positive antiphospholipid syndrome and systemic lupus erythematosus dendritic cells." (PMID 30854012, 2019). "Furthermore, the pharmacological activation of spinal GPR109A receptors in microglia in lupus mice suppresses chronic pain by inhibiting p38 MAPK activity and the production of both IL-1β and IL-18, as well as reducing glutamatergic synaptic activity in the spinal dorsal horn." (PMID 38612414, 2024). "Conversely, in spinal slices from lupus mice, following confirmation of the enhanced glial glutamate transporter activity by the CSF-1R inhibitor, the additional inhibition of IL-1β through bath perfusion of IL-1ra did not produce a significant alteration in glial transporter activity." (PMID 38612414, 2024). "Furthermore, NZB mice exhibited an increase in IL-1β and IL-17A concentrations and the Th17/Treg cell ratio following injection of anti-dsDNA antibodies, suggesting that the NLRP3 inflammasome is involved in lupus pathogenesis in mice." (PMID 32528469, 2020). "Together, these data suggest that whereas IL-1β does not affect overall survival or autoantibody production in lupus-prone mice, it may play an important sex-specific protective role in the kidney by limiting immune complex deposition and resultant proteinuria." (PMID 37261358, 2023). "Moreover, the increased IL-1β and ASC expression can be detected in the colon of patients with inflammatory bowel diseases (IBDs), while systemic lupus erythematosus (SLE) patients exhibit an increased level of NLRP3 proteins in macrophages and tissues." (PMID 35883561, 2022). "This case control study used 46 KOA patients (pKOA, n = 30; sKOA, n = 16), and 60 age, gender matched controls (normal healthy, n = 30; systemic lupus erythematosus [SLE] disease controls, n = 30) where serum was assayed for cytokines (TNF-α, IL-1β, IL-6, IL-10) and nitric oxide derivatives (NOx)." (PMID 34543351, 2021). "Certain cytokines previously associated with HRV in experimental models of acute inflammation, such as TNF-α and IL-1β, were not impacted by HRV in this study of patients with lupus." (PMID 27590046, 2016). "It is notable that IL‐38 injection significantly reduced the levels of inflammatory cytokines IL‐1β, TNF‐α, IL‐6 and IL‐23 in plasma, demonstrating that IL‐38 is able to protect mice from lupus development, and has a negative role in regulating inflammatory cytokines both in vitro and in vivo." (PMID 33079487, 2020). "Compared to those in SLE patients without renal damage, patients with lupus nephritis (LN) exhibited lower mRNA levels of NEK7, NLRP3, and ASC but higher levels of Caspase-1, IL-1b, and IL-18." (PMID 30202244, 2018).
steatosis (113 papers, 2008 to 2026). Increased lipid within the cytoplasm of cells. "Preclinical models of ALD have shown upregulation of IL-1β in the liver, and pharmacological blockade of IL-1 signaling has been associated with reduced liver injury, steatosis, and inflammation." (PMID 41163775, 2025). "IL-1β leads to hepatic triglyceride accumulation (steatosis) and is associated with increased pro-inflammatory cytokine expression in MASLD." (PMID 38755697, 2024). "In this study, we evaluated the possible pathogenic roles of NLRP3 and IL-1β in the development of steatosis and fibrosis in patients with MAFLD." (PMID 39179677, 2024). "Feeding alcohol to MCP-1–deficient mice results in less steatosis, lower expression of pro-inflammatory cytokines (i.e., of TNFα, IL-1β, and IL-6), and lower levels of oxidative stress than in wild-type mice." (PMID 26695748, 2015). "This association is further supported by the observation that steatosis can be prevented when innate immune responses are experimentally abrogated by checking IL-1β or MCP-1 activity." (PMID 26695748, 2015). "In this regard, a Japanese cohort revealed that the gain-of-function of the IL-1β-511C>T rs16944 variant plays a major role in the development of NAFLD through its involvement in disease stages ranging from simple steatosis’ progression toward NASH and fibrosis." (PMID 38504356, 2024). "Il1β is a pivotal proinflammatory cytokine that causes liver inflammation, steatosis, and injury." (PMID 34681600, 2021). "However, in a similar alcohol-related liver diseases mouse model with a deficiency for NLRP3, steatosis, inflammation, IL-1β expression, and number of activated natural killer T cells are all decreased, highlighting NLRP3 role in the pathogenesis of alcohol-related liver disease." (PMID 34650994, 2021). "Treatment with Que-CH significantly reduced serum IL-1β, improved liver histology by decreasing macro- and microvesicular steatosis, and lowered the Bax/Bcl-2 ratio, indicating reduced hepatocyte apoptosis." (PMID 41971603, 2026). "CD47 deficiency enhances NF-κB activation, elevates IL-1β, TNFα, IL-6, reduces IL-10, increases CCL2 and macrophage infiltration, leading to exacerbated steatosis, inflammation, and fibrosis." (PMID 40630093, 2025). "In preclinical animal models, administration of IL-1β inhibitors, including IL-1 receptor antagonists (IL-1RA) or anti-IL-1β antibodies, has been shown to mitigate liver inflammation, steatosis, and fibrosis." (PMID 40399593, 2025). "Through a variety of mechanisms, including steatosis promotion, insulin signaling disruption, fibrotic protein synthesis by stellate cells, and neutrophil recruitment, IL-1β contributes to the pathogenesis of non-alcoholic steatosis." (PMID 39179677, 2024). "The pro-inflammatory cytokine IL-1β plays a critical role in the onset and progression of the non-alcoholic fatty liver disease; from simple steatosis to non-alcoholic steatohepatitis and hepatic fibrosis." (PMID 39179677, 2024). "Enhance the expression of ZO-1, Claudin-1 and Occludin, decrease the expression of LPS, TNF-α, IL-6 and IL-1β, enhance intestinal barrier, and reduce inflammatory response, hepatocyte steatosis and collagen fiber deposition." (PMID 39234554, 2024). "We found that IL-1β in liver increased as reperfusion occurs and such enhancement was more apparent in the presence of steatosis." (PMID 37593740, 2023). "NLRP3 and mature IL1β levels were also elevated in the livers of patients with steatosis and NASH compared with livers from healthy controls." (PMID 37739179, 2023). "Consistent with this study, we found that the decreased level of IL-1β was accompanied by the ameliorated steatosis and ballooning liver injury and less MPO positive cells when supplementation of MFGM in rats." (PMID 35308293, 2022). "Hepatic and extra-hepatic sources of IL-1β, upregulated by activated macrophages, contribute to metabolic liver inflammation steatosis and fibrosis." (PMID 35165344, 2022).
steatosis (continued). "Binge drinking of ethanol led to weight loss in the body and spleen, liver inflammation and steatosis, and increased serum ALT and AST levels (markers of liver injury), along with increased IL-1β, TNF-α, and iNOS expression levels in mice." (PMID 35165521, 2022). "IL-1β promotes steatosis by inhibiting fatty acid oxidation via PPARα and promotes TG synthesis, accumulation and lipid droplet formation in hepatocytes." (PMID 34956171, 2021). "Despite the persisting steatosis, tempol administration completely prevented the induction of key pro-inflammatory (Tnfα and Il-1β) and fibrogenic (Tgfβ and αSMA) markers, suggesting a liver protecting effect." (PMID 34427662, 2021). "IL-1β secreted by KCs in alcohol-related liver disease mouse models aggravates steatosis and fibrosis." (PMID 34650994, 2021). "Swimming treatment attenuated these pathological changes in liver tissue, reducing the incidence of steatosis and cell ballooning and suppressing il1β and tnfα expression." (PMID 34681600, 2021). "Mice with hepatocyte-specific CD147 deletion exhibited attenuated NASH phenotypes, including reduced steatosis, liver injury, hepatocyte apoptosis and inflammatory cytokines IL-1β/IL-18 secretion." (PMID 32903542, 2020). "This regulation induces the production of various pro-inflammatory cytokines, such as TNF-α, interferon gamma (IFN-γ), and IL-1β, which are critically regulated hepatic inflammation, steatosis, fibrosis, and HCC." (PMID 32143357, 2020). "The steatosis was also accompanied by an increase in the expression of pro-inflammatory interleukins (IL), IL-1β and TNF in PCLS." (PMID 32094147, 2020). "In contrast, inhibition of IL-1β was found to attenuate steatosis and liver injury, improve atherosclerosis, and lower glycemia." (PMID 31736870, 2019). "Macrophage produced cytokines (e.g., IL-6, TNF, IL-1β) can directly target hepatocytes and promote steatosis, inflammation and hepatocellular damage." (PMID 31921154, 2019). "IL-1β mRNA was significantly induced in patients with steatosis or NASH compared to healthy controls but IL-1β expression was 20% lower in NASH livers compared to steatosis livers." (PMID 30382148, 2018). "In line with this, hepatic GDF15 expression directly correlated with IL-1β expression and steatosis severity in NAFLD." (PMID 30533221, 2018). "(iv) Hepatic GDF15 expression directly correlates with features of human NAFLD i.e., IL-1β expression and steatosis." (PMID 30533221, 2018). "The expression of the IL-1β mRNA negatively correlated with NASH activity score (NAS) in patients with steatosis or NASH." (PMID 30382148, 2018). "In a murine model, increasing TNFα and IL-1β production were observed in alcohol-fed mice that neutralize IL-1β in KCs to allowed iNKT cell accumulation and steatosis." (PMID 30425710, 2018). "IL-1β has been shown to have a role in the transformation of steatosis to steatohepatitis and liver fibrosis." (PMID 27739482, 2016). "These processes lead to the production of several pro-inflammatory cytokines (e.g., of TNFα, IL-1β, IL-8, and IL-17), triggering steatosis in hepatocytes and inducing fibrogenic pathways in HSCs." (PMID 26695748, 2015). "Infliximab (anti-TNF-α) reverses the steatosis and the expression of the proinflammatory markers (TNF-α, IL6, IL-1B) and improves insulin signal trasduction in a model of steatosis in rats." (PMID 18782455, 2008). "IL-1β is currently regarded as a key regulator of tissue injury and inflammation in chronic liver disorders because of its critical role in the transformation of steatosis into steatohepatitis and LF." (PMID 40291773, 2025). "Additionally, MAFLD patients with advanced steatosis showed a significant increase in the expression IL-1β levels." (PMID 39179677, 2024). "Furthermore, IL-1β gene expression increases in livers of mice fed a high-fat, high-cholesterol (1.25%) diet for 18 weeks, and deletion of IL-1β reduces steatosis, inflammation, ballooning, and fibrosis in these mice." (PMID 37200978, 2023).
steatosis (continued). "In addition, the expression of hepatic GDF15 in NAFLD directly correlates with IL-1β content and the severity of steatosis." (PMID 35845807, 2022). "IL-1β could promote hepatocytes to take up fatty acids, synthesize TG, and aggravate the steatosis of liver." (PMID 35586044, 2022). "As an immune mediator, IL-1β might not only promote fat accumulation in the liver and induce hepatocyte steatosis but also activate stellate cells and amplify inflammation-induced Ccl2, Tnf, and Il1b expression." (PMID 36426356, 2022). "IL-1β might contribute to the pathogenesis of liver damage as IL-1β knockout mice showed attenuated hepatocellular damage, steatosis, and fibrosis in atherogenic diet-induced steatohepatitis." (PMID 33935806, 2021). "In addition, CeO2-NCs reported reducing steatosis, lobular inflammation and pro-inflammatory cytokines (IL-1β, IL-12Bp40) in rat serum." (PMID 33806527, 2021). "This strong association of IL-1β with disease severity is also reflected in the circulation, as elevated blood-levels of IL-1β are found in patients with NASH, compared to those with simple steatosis." (PMID 33633748, 2020). "In addition to steatosis, RT-qPCR analysis revealed an increased expression of hepatic Il1b and an almost significant increase in Tnf (p = 0.08)." (PMID 33374541, 2020). "IL-1β plays a key role in liver disease, as it affects both steatosis, inflammation and fibrosis." (PMID 33633748, 2020). "Furthermore, Quer reduced liver lipid steatosis and inhibited the expression of proinflammatory cytokines, such as tumor necrosis factor-α, IL-6, and IL-1β." (PMID 33076582, 2020). "IL-1β is also involved in the progression of NAFLD including steatosis." (PMID 31788011, 2019). "IL-1β is considered to mediate inflammation, steatosis, and fibrosis in liver." (PMID 31736870, 2019). "IL-1β contributed to metabolism disorder, liver injury and steatosis in animal experiments." (PMID 30429827, 2018). "Treating mice with BAR501 improved liver histopathology leading to a 50–70% reduction in the steatosis, fibrosis and inflammatory scores, along with reduction of inflammatory (Il-1β, Il-6, Tnfα, Mcp-1, Rantes and F4/80) and fibrogenic (αSma and Col1α1) genes (P < 0.05)." (PMID 29057935, 2017). "Since ER stress-induced steatosis and lipid accumulation were affected by inflammasome activities, we hypothesize that ER stress-induced inflammasome activation and IL-1β regulate liver function and lipid metabolism." (PMID 27942420, 2016). "Although enhanced inflammation in liver of C57Bl/6 mice and proinflammatory cytokines such as IL-1β may affect lipid metabolism and increase fatty acid biosynthesis in liver, we showed that steatosis in C57Bl/6 mice was scarce." (PMID 26218873, 2015). "Additionally, IL-1β KO mice are protected from diet-induced steatosis, whereas IL-1α KO mice develop steatosis." (PMID 25216251, 2014). "Indeed, IL-1β in NAFLD contribute to steatosis’ progression toward NASH and fibrosis." (PMID 38504356, 2024). "In grafts in the absence of steatosis obtained from DBDs, we observed that the administration of exogenous NO (BD+NO+LT) increased IL-6 and that this was associated with reduced IL-1β levels and protection against hepatic damage and inflammation, compared to the BD+LT group." (PMID 37593740, 2023). "In the present research, similarly to that occurring with IL-1β at 4 h after transplantation, supplying a NO donor at the same dose in both liver types led to different results: NO donor was beneficial in non-steatotic livers but resulted in detrimental effects in the presence of steatosis." (PMID 37593740, 2023). "For this, we evaluated whether the increased IL-1β levels were responsible for the exacerbated damage induced by the inhibition of either IL-6 or IL-10 action in liver grafts from DBDs, in the absence and presence of steatosis, respectively." (PMID 37593740, 2023). "Moreover, IL-1β-deficient mice during NAFLD had reduced inflammation and steatosis in the liver." (PMID 31500117, 2019).
steatosis (continued). "Increased expression of IL-1β and TNF-α receptors in MO offspring suggest that maternal developmental programming induces a predisposition to hepatic inflammatory responses which may contribute to long term risk of hepatic IR, steatosis and fibrosis." (PMID 24146946, 2013). "Liver histology showed amelioration of steatosis and inflammation, as evidenced by reduced MAFLD activity score and decreased intrahepatic expression of IL-1β and IL-17α mRNA." (PMID 41836291, 2026). "SIRT1 deficiency triggers the activation of the NF-κB pathway, leading to increased expression of inflammatory factors like IL-1β, IL-6, and TNF-α, accelerating the progression of NAFLD from simple steatosis to steatohepatitis." (PMID 39949396, 2024). "As a critical hallmark of NAFLD, immune cells typically increase at the transition from steatosis to NASH, leading to fibrosis through the release of cytokines like IL-6, IL-1β, IL-17, IL-22, TGF-β, and tumor necrosis factor-α (TNF-α)." (PMID 39273539, 2024). "Blocking IL-1β signaling markedly mitigates inflammation, steatosis, and fibrosis in a mouse model of ALD, which indicates that IL-1β is a potential target for AH." (PMID 38971765, 2024). "TNF and IL-1β are key cytokines in MASLD, driving the development of steatosis, inflammation and fibrosis, and the majority TNF and IL-1β molecules in the liver are derived from activated macrophages." (PMID 39372417, 2024). "We showed that β-sitosterol reduced steatosis and the serum levels of triglycerides, transaminases (ALT and AST) and inflammatory markers (IL-1β and iNOS) compared to HFD-fed rats." (PMID 37173727, 2023). "In conclusion, it seemed, after review, that most of the mentioned cellular and soluble mediators, with the exception of TNFα, IL-1β, IL-6 and hs-CRP, were more related to inflammation and fibrosis than steatosis itself." (PMID 36768637, 2023). "Compared with the control group, inulin reduced the steatosis lipid synthesis genes (CHREBP, Srebp-1c, FASN, and Scd-1) in mice fed a HFD and also significantly decreased the expressions of IL-6, IL-1β, and TNF-1α in the liver." (PMID 37554983, 2023). "Inhibition of IL-1β or deletion of ASC and caspase-1 ameliorate inflammation, steatosis and liver injury in mice." (PMID 35173541, 2022). "Given that classically activated M1 macrophages showed increased levels of pro-inflammatory cytokines, including interleukin 1-β (IL-1β), tumor necrosis factor α (TNF α), interleukin 6 (IL6), which induce hepatic damage and steatosis." (PMID 35143415, 2022). "NFKBIA overexpression is related to steatosis development by induction of hepatocyte apoptosis and secretion of TNF-α and IL-1β by Kupffer cells." (PMID 33785040, 2021). "Firstly, the palmitate acid-induced hepatocytes steatosis involved the activation of NLRP3 inflammasome and increased secretion of IL-1β and IL-18." (PMID 32477116, 2020). "In the present study, with the reduction in the TNF-α and IL-1β expression, much fewer Mac-2- and α-SMA-positive cells were observed in the livers of AG mice with simple steatosis than in NG mice showing progression to NASH." (PMID 31835339, 2019). "HFD significantly increased total fat and triacylglyceride contents with macrovesicular steatosis, concomitantly with higher fasting serum glucose and insulin levels, HOMA, and serum TNF-α, IL-1β, and IL-6." (PMID 23082120, 2012). "IL-1β then upregulates SREBP-1c, enhancing lipogenic gene transcription and aggravating steatosis." (PMID 40988029, 2025). "This study aimed to investigate the expression levels of NLRP3 inflammasome and IL-1β genes in the blood of patients with MAFLD with various degrees of fibrosis and steatosis to provide new insights into the possible role of the NLRP3 inflammasome pathway in the pathogenesis of MAFLD." (PMID 39179677, 2024). "In this study IL-1β and NLRP3 were more sensitive than steatosis in the detection of fibrosis." (PMID 39179677, 2024).